ENTPD1 (ectonucleoside triphosphate diphosphohydrolase 1)
Diseases named in the same sentence as ENTPD1 in open-access papers (continued):
Sharing a sentence is not in itself a finding about the gene and the disease.
Crohn disease (20 papers, 2011 to 2026). A gastrointestinal disorder characterized by chronic inflammation involving all layers of the intestinal wall, noncaseating granulomas affecting the intestinal wall and regional lymph nodes, and transmural fibrosis. "CD39 is further involved in the pathogenesis of IBD, as polymorphisms in the ENTPD1 gene are associated with increased susceptibility to Crohn’s disease in humans and CD39-deficiency exacerbates disease severity in murine IBD models." (PMID 38567057, 2023). "In humans, single nucleotide polymorphisms of the human ENTPD1 gene that lead to a decreased expression of CD39 are associated with increased susceptibility to Crohn’s disease." (PMID 33072107, 2020). "Accordingly, high ENTPD1/CD39 expression by circulating Tregs correlates with clinical remission in IBD patients while single nucleotide polymorphisms, associated with low Entpd1/Cd39 mRNA levels, increase predisposition to Crohn's disease." (PMID 30941139, 2019). "Furthermore, the presence of genetic polymorphisms of ENTPD1 and also levels of expression of CD39 on Tregs, have been associated with increased susceptibility to Crohn’s disease in humans and in predicting the response to immunomodulatory therapy, respectively." (PMID 30691212, 2019). "In Crohn’s disease, levels of ENTPD1 and IL10 were higher in Th17 cells exposed to UCB and FANA-PGK1 or FANA-ALDOA than in those exposed to UCB alone; this increase was significant in the case of IL10 and trended towards significance for ENTPD1." (PMID 36131123, 2022). "Experimental and clinical evidences indicate a protective role of ENTPD1/CD39 in Crohn's disease (CD)." (PMID 30941139, 2019). "The function of the ENTPD1 was regarded as important modulators of the immune system, contributing to the balance between regulatory and effector lymphocytes in rheumatoid arthritis, Crohn’s disease, and autoimmune hepatitis." (PMID 37784152, 2023). "CD3/CD28-mediated stimulation of IFN-γ-producing CD8+ T-cells, another effector subset involved in Crohn's disease pathogenesis, not only increases IFN-γ production by CD8 T-cells, but also induces reactive oxygen species and ENTPD1/CD39 expression." (PMID 30941139, 2019). "We have recently reported that in vitro exposure to unconjugated bilirubin (UCB), a product of heme oxidation that serves as AhR endogenous ligand, results in increased levels of ENTPD1/CD39 and FOXP3 in Th17-cells derived from healthy individuals but not from Crohn's disease patients." (PMID 30941139, 2019).
glioblastoma (18 papers, 2020 to 2026). The most malignant astrocytic tumor (WHO grade IV). "Reinforcing these results, a strong and positive correlation was observed between HAVCR2 and ENTPD1 expression levels in glioblastoma patients." (PMID 39513882, 2024). "Moreover, elevated HAVCR2 (but not ENTPD1) expression levels were significantly associated with reduced progression-free survival (PFS), but not overall survival for glioblastoma patients." (PMID 39513882, 2024). "Cell surface TIM-3, but not ENTPD1, was also elevated on activated CD4+ and CD8+ T cells, as well as on NK cells from glioblastoma patients compared to healthy donor T and NK cells." (PMID 39513882, 2024).
inflammatory bowel disease (18 papers, 2012 to 2025). A spectrum of small and large bowel inflammatory diseases of unknown etiology. "However, human adults with a frequent SNP at the position rs10748643 of the ENTPD1 gene are largely healthy with the exception of an increased susceptibility to inflammatory bowel disease." (PMID 35730568, 2022). "In this review, we will discuss the role of the purinergic signaling, with a focus on P1 and P2 receptors and on ENTPD1/CD39 and CD73 ectoenzymes, in the context of inflammatory bowel disease (IBD)." (PMID 33072065, 2020).
non-small cell lung carcinoma (18 papers, 2018 to 2025). A group of at least three distinct histological types of lung cancer, including non-small cell squamous cell carcinoma, adenocarcinoma, and large cell carcinoma. "ENTPD1 is elevated in intratumoral immune cells of non-small cell lung cancer." (PMID 36233136, 2022). "There is abundant evidence that ENTPD1 and NT5E expression are increased in cancer including in gastric cancer, non-small cell lung cancer and prostate cancer." (PMID 36233136, 2022).
head and neck squamous cell carcinoma (17 papers, 2016 to 2025). A squamous cell carcinoma that arises from any of the following anatomic sites: lip and oral cavity, nasal cavity, paranasal sinuses, pharynx, larynx, and salivary glands. "Pathological research has shown that the expression of ENTPD1 in head and neck squamous cell carcinoma (HNSCC) is positively correlated with tumor stage, which may predict a poor prognosis." (PMID 34115774, 2021).
Stroke (17 papers, 2015 to 2025). Sudden impairment of blood flow to a part of the brain due to occlusion or rupture of an artery to the brain. "The ENTPD-1 (CD39) expression was elevated in the ipsilateral hemisphere 7 days post-stroke compared to in the contralateral hemisphere and compared to days 1 and 3 (p < 0.05)." (PMID 40332314, 2025). "Therefore, Entpd1 may affect the recovery of nerve function and immune response by regulating the concentration of adenosine in ischemic stroke, and inhibiting its activity may have potential positive effects on the treatment of stroke." (PMID 39942654, 2025). "However, there is a significantly higher expression of two ectonucleotidases (ENTPD-1, CD39 and NT5E, CD73) in the ipsilateral hemisphere 7 days after stroke." (PMID 40332314, 2025).
rheumatoid arthritis (16 papers, 2016 to 2025). A chronic, systemic autoimmune disorder characterized by inflammation in the synovial membranes and articular surfaces. "The expression of ENTPD1 in CD4+ and CD8+ T cells and B cells showed associations with disease activity indices in individuals with rheumatoid arthritis (RA)." (PMID 38612896, 2024). "KEGG pathway analysis of the upregulated proteins in ENTPD1+CD55+ cells indicated enrichment for proteins involved in rheumatoid arthritis (e.g., HLA-DRA, ICAM1) and ECM–receptor interaction (e.g., type I collagen, Laminin subunit alpha-5, integrin-subunit alpha-6)." (PMID 38612896, 2024).
Autoimmunity (13 papers, 2016 to 2025). The occurrence of an immune reaction against the organism's own cells or tissues. "As already observed in other autoimmune conditions, promising therapeutic candidates based on adenosine or ENTPD1/CD39 and CD73 ectonucleotidases have been identified." (PMID 33072065, 2020). "In this review, we will discuss the role of ENTPD1/CD39 and CD73 ectoenzymes and focus on the effects of extracellular adenosine on P1 receptors, in the context of systemic and organ-specific autoimmune conditions." (PMID 30691212, 2019).
metastatic tumors (13 papers, 2014 to 2024). "ENTPD1 expressed on CD4+Foxp3+ regulatory T cells (Tregs), and in mice, it could inhibit natural killer (NK) cells and promote hepatic metastatic tumor growth, whereas inhibition of the enzymatic activity of ENTPD1 could be used as an adjunct therapy for hepatic malignancies." (PMID 36998605, 2023).
Arthritis (11 papers, 2014 to 2023). Inflammation of a joint. "Interestingly, studies conducted in murine models of arthritis have shown that CD39 blockade and decreased adenosine generation reverse the therapeutic effect of MTX, while non-responder patients express lower pre-treatment levels of CD39/ENTPD1." (PMID 30691212, 2019).
gastric cancer (11 papers, 2019 to 2025). A primary or metastatic malignant neoplasm involving the stomach. "ENTPD1 was also expressed at higher rate in gastric cancer tissue, and over-expression correlated with poor overall survival." (PMID 34465393, 2021).
myocardial infarction (11 papers, 2013 to 2025). Gross necrosis of the myocardium, as a result of interruption of the blood supply to the area, as in coronary thrombosis. "Such counter-intuitive observations were reported in a permanent coronary ligation model of myocardial infarction where Entpd1−/− mice showed less mortality and cardiac rupture." (PMID 37894719, 2023).
ischemic stroke (10 papers, 2015 to 2025). A stroke disorder caused by obstruction of blood flow to the brain, due to thrombotic (local blood clot formation) or embolic (due to a blood clot or other material traveling from another site) event. "Studies have shown that inhibiting the activity of Entpd1 can promote the recovery of neural function in the mouse model of ischemic stroke, because inhibiting Entpd1 reduces the production of extracellular adenosine, thus alleviating the inhibitory effect of adenosine on neural function." (PMID 39942654, 2025). "According to the literature review, the core proteins identified, such as Adk, Aprt, Entpd1, and Pde4d, are closely related to the pathogenesis and treatment of ischemic stroke, opening a new path and providing solid theoretical support for the subsequent exploration of pharmacodynamic mechanisms." (PMID 39942654, 2025).
lupus (10 papers, 2018 to 2026). "In the experimental mice model of lupus, the suppression of neutrophil extracellular trap release mediated by ENTPD1 was observed." (PMID 37895880, 2023). "ENTPD1/CD39−/− and CD73−/− mice show more pronounced endothelial cell dysfunction and exaggerated neutrophil extracellular “trap” release in response to intraperitoneal administration of pristane, in a model of lupus, when compared to wild type (WT) controls." (PMID 30691212, 2019).
Obesity (10 papers, 2015 to 2024). Accumulation of substantial excess body fat. "To further explore whether AT T cells contain an exhausted signature following obesity, we generated an exhaustion module containing multiple established gene expression features of T cell exhaustion: Pdcd1, Tox, Entpd1, Tigit, and Lag331,32." (PMID 35618862, 2022). "Similar to Emr1, higher levels of Entpd1, Cd38, and Nt5e were found in BAT of ob/ob mice, while no obesity-associated changes in Ucp1 expression were detected." (PMID 33025427, 2020).
prostate carcinoma (10 papers, 2022 to 2025). A carcinoma that arises from epithelial cells of the prostate gland. "A 3-gene signature composed of ENTPD1, NT5E, and ADORA3 is associated with a greater chance of bone metastasis in ER+ breast and prostate cancers." (PMID 36186774, 2022). "We showed that expression of a three-gene expression signature comprising ENTPD1, NT5E, and ADORA3 in primary ER+ breast and prostate cancers was correlated with bone metastases." (PMID 36186774, 2022). "We also analyzed gene expression in metastatic prostate cancer (GSE74685) and found a similar expression pattern, with ENTPD1, NT5E, and ADORA3 upregulation in bone metastases than in other metastases, bottom." (PMID 36186774, 2022).
esophageal squamous cell carcinoma (8 papers, 2021 to 2025). Esophageal squamous cell carcinoma (ESCC) is a type of esophageal carcinoma (EC) that can affect any part of the esophagus, but is usually located in the upper or middle third. "The study found that IL-6 could induce ENTPD1 expression on tumor-infiltrating NK cells, which predicted a poor prognosis in esophageal squamous cell carcinoma." (PMID 34465393, 2021).
thyroid cancer (7 papers, 2021 to 2025). "The expression of ENTPD1 was relatively higher in thyroid cancer than in other cancers." (PMID 34465393, 2021). "However, medium staining and strong intensity of ENTPD1 protein expression was observed in thyroid cancer tissue." (PMID 34465393, 2021). "Most of cases in thyroid cancer showed the high expression of ENTPD1 protein." (PMID 34465393, 2021). "Nevertheless, the exact role of ENTPD1 in thyroid carcinoma (THCA) remained unclear." (PMID 34465393, 2021). "It followed that ENTPD1 might play a vital role in thyroid carcinoma through regulating important pathways." (PMID 34465393, 2021). "Our study indicated the ENTPD1 as a significant biomarker involved in thyroid carcinoma." (PMID 34465393, 2021). "Thus, the specific functions of ENTPD1 in thyroid cancer should be further explored." (PMID 34115774, 2021). "Thus far, there have been a few reports on the relationship between ENTPD1 and thyroid cancer." (PMID 34115774, 2021).
endothelial dysfunction (6 papers, 2015 to 2025). In vascular diseases, endothelial dysfunction is a systemic pathological state of the endothelium (the inner lining of blood vessels) and can be broadly defined as an imbalance between vasodilating and vasoconstricting substances produced by (or acting on) the endothelium. "Conversely, MRA and LCA from Entpd1−/− mice showed a slight alteration in the submaximal responses to Ach, suggesting an endothelial dysfunction in the small diameter resistance arteries." (PMID 37894719, 2023). "This suggests an apparent endothelial dysfunction in Entpd1−/− mesenteric arteries which involves a COX-related endothelial-derived relaxing factor, likely pointing to PGI2/prostacyclin." (PMID 37894719, 2023).
Hypertension (6 papers, 2007 to 2024). The presence of chronic increased pressure in the systemic arterial system. "We have also identified 8 important genes (NME4, PNPLA7, GGT5, PTGS2, IGF1R, NT5C2, ENTPD1 and PTEN), a number of gene ontology categories and biological pathways that may be associated with military pilot hypertension." (PMID 29996846, 2018). "We have also identified 8 important genes (NME4, PNPLA7, GGT5, PTGS2, IGF1R, NT5C2, ENTPD1 and PTEN), a few GO categories and biological pathways that may be associated with the military pilot hypertension." (PMID 29996846, 2018). "Their results strongly suggested that down-regulation of ENTPD1 may be a sign of hypertension, consistent with our results." (PMID 29996846, 2018). "The results from Western blotting showed that NME4 and PNPLA7 these two genes were up-regulated significantly and GGT5, PTGS2, IGF1R, NT5C2, ENTPD1 and PTEN these six genes were down-regulated significantly in PBMCs of military pilots with hypertension." (PMID 29996846, 2018).
idiopathic pulmonary fibrosis (6 papers, 2018 to 2025). Idiopathic pulmonary fibrosis (IPF) is a nonneoplastic pulmonary disease that is characterized by the formation of scar tissue within the lungs in the absence of any known cause. "‘COL23A1+ adventitial fibroblasts’ shared key markers (COL15A1, ENTPD1, PLCL1) with peribronchial fibroblasts, a subpopulation specifically localized around the airway epithelium, which is enriched in idiopathic pulmonary fibrosis and may be implicated as a key cell type in lung disease." (PMID 40114924, 2025). "According to the results of qRT-PCR, the expression levels of ENPP3, PDE7B, and ENTPD1 were elevated, while the expression levels of PNMT, GPX3, and POLR3H were decreased in the lung tissues of bleomycin-induced pulmonary fibrosis mice compared with the sham group." (PMID 36923791, 2023).
Insulin resistance (6 papers, 2014 to 2024). Increased resistance towards insulin, that is, diminished effectiveness of insulin in reducing blood glucose levels. "Entpd1/Cd39 deletion correlates with increased insulin resistance and aberrant hepatic glucose metabolism." (PMID 30941139, 2019).
liver cancer (6 papers, 2019 to 2024). An epithelial or non-epithelial malignant neoplasm that arises from the liver. "Further experimentation suggests the development of autochthonous liver cancer in Entpd1/Cd39−/− mice, resulting from comparable eATP-P2 receptor-mediated changes: inclusive of suppression of liver cell autophagy, altered metabolism, and boosting of proliferation." (PMID 30941139, 2019). "ENTPD1, the most investigated member of the ENTPD family, repressed tumorigenesis and the progression of liver cancer via the degradation of eATP which boosted the Ras-mitogen-activated protein kinase pathway." (PMID 31754326, 2019).
malaria (6 papers, 2009 to 2024). Malaria is a serious and sometimes fatal disease caused by a parasite that commonly infects a certain type of mosquito which feeds on humans. "Of note, several metabolic-related molecules such as P2rx7 (encoding P2X7) and Entpd1 (encoding CD39) were found to correlate with Th1 and Tfh cell bifurcation in malaria." (PMID 36845571, 2021).
Hepatitis (5 papers, 2019 to 2024). Inflammation of the liver. "In murine models of Concanavalin-A induced hepatitis, genetic deletion of Entpd1/Cd39 promotes eATP/P2X7-mediated NKT apoptosis and paradoxically provides protection from liver injury." (PMID 30941139, 2019).
pulmonary arterial hypertension (5 papers, 2018 to 2024). Pulmonary arterial hypertension (PAH) is a group of diseases characterized by mean pulmonary artery pressure >20 mmHg and elevated pulmonary arterial resistance leading to right heart failure. "Moreover, mice lacking ENTPD1 activity develop pulmonary arterial hypertension, and remodeling, as well as ventricular hypertrophy, following hypoxia." (PMID 37895880, 2023).
relapsing-remitting MS (5 papers, 2018 to 2021). "Around 40% of relapsing-remitting MS cases present with apparent Th17-cell expansion with a positive correlation between Th17-cell numbers and ENTPD1/CD39+ Treg frequencies during remission but not during relapse." (PMID 30691212, 2019).
esophageal cancer (4 papers, 2023 to 2025). A primary or metastatic malignant neoplasm involving the esophagus. "The TIMER database also showed consistent results that ENTPD1 expression was significantly positively correlated with the infiltration abundance of CD8+ T cells in esophageal carcinoma (p = 0.028)." (PMID 36831526, 2023). "In the TISIDB database, ENTPD1 expression in esophageal carcinoma was shown to be statistically positively correlated with the expression of currently recognized inhibitory immune checkpoint molecules PDCD1 (p < 0.001), CTLA4 (p < 0.001), and HAVCR2 (p < 0.001)." (PMID 36831526, 2023). "Furthermore, ENTPD1 expression in esophageal carcinoma tissues was positively correlated with the expression of genetic markers of multiple TIICs, including CD8A and CD8B of CD8+ T cells, with or without adjustment for tumor purity." (PMID 36831526, 2023). "Furthermore, ENTPD1 expression in the esophageal carcinoma was found to be positively correlated with both subtypes of CD8+ T cells: active CD8+ T cells (p < 0.001) and memory CD8+ T cells (p < 0.001)." (PMID 36831526, 2023). "The results of the TISIDB database showed that ENTPD1 expression was significantly positively correlated with the abundance of TIICs in the TME of most types of tumors, including esophageal carcinoma." (PMID 36831526, 2023). "Moreover, we found that the expression level of ENTPD1 was positively correlated with the infiltrating abundance of CD8+ T cells and the expression level of inhibitory immune checkpoint molecules PDCD1, CTLA4, and HAVCR2 in esophageal carcinoma, but not in normal tissues." (PMID 36831526, 2023).
liver fibrosis (4 papers, 2020 to 2026). "Shuai et al146 identified a novel, purinergic mechanisms by which ectonucleoside triphosphate diphosphohydrolase-1/ENTPD1 (CD39)–mediated ATP-adenosine signaling regulates TGF-β/Smad3 signaling during HSC-T6 activation and alcohol-related liver fibrosis." (PMID 41109667, 2026).
lung adenocarcinoma (4 papers, 2018 to 2025). A carcinoma that arises from the lung and is characterized by the presence of malignant glandular epithelial cells. "To confirm our data, we interrogated the TCGA data sets for HNSCC, lung adenocarcinoma, and lung squamous cell carcinoma, comparing patients with high expression of ENTPD1 (CD39) and ITGAE (CD103) transcripts to patients with lower expression of those genes." (PMID 30006565, 2018).